IGKJ3 (immunoglobulin kappa joining 3)
Synonyms: J3
Gene: Immunoglobulin joining (J) gene on chromosome 2 (88,861,221 to 88,861,258, reverse strand). Ensembl gene ENSG00000211595.
Diseases named in the same sentence as IGKJ3 in open-access papers:
IGKJ3 is named in the same sentence as 6 diseases in open-access papers, as found by Europe PMC text mining. Sharing a sentence is not in itself a finding about the gene and the disease. The quoted sentences say what the papers report.
acute myeloid leukemia (1 paper, 2025). Acute myeloid leukemia (AML) is a group of neoplasms arising from precursor cells committed to the myeloid cell-line differentiation. "In hematologic cancers like acute myeloid leukemia (AML), the IGKV1-5/IGKJ3*01 rearrangement in myeloblasts upregulates fLMP and CXCL12, chemotactic factors that drive AML cell migration and dissemination." (PMID 40806736, 2025).
colon cancer (1 paper, 2025). "Igκs derived from breast cancer, colon cancer, lung cancer, and hepatocellular carcinoma were further confirmed to predominantly utilize a unique IGKV4-1/IGKJ3 rearrangement pattern." (PMID 40806736, 2025).
IGKJ3 also shares sentences with these, for which no sentence is quoted: infection (2 papers); hepatocellular carcinoma (1); lung carcinoma (1); virus infection (1).